ID2 (inhibitor of DNA binding 2)
Diseases named in the same sentence as ID2 in open-access papers (continued):
Sharing a sentence is not in itself a finding about the gene and the disease.
renal fibrosis (3 papers, 2013 to 2022). A final common manifestation of a wide variety of chronic kidney diseases characterized by glomerulosclerosis and tubulointerstitial fibrosis. "Thus, we speculated that oxymatrine promoted the recovery of Id2, which inhibited Twist itself or affected the gene regulation of Twist, and play an anti-diabetic role in renal fibrosis." (PMID 32636757, 2020). "Similarly, it is unclear whether TGFβ1 could control α-SMA expression through regulating Id2 in a human epithelial cell type relevant to renal fibrosis." (PMID 23320068, 2013). "Since these growth factors play a pivotal role in the regulation of renal fibrosis by regulating PTEC phenotype, we investigated the regulation of Id2 by these two growth factors in relation to the expression of key markers of EMT." (PMID 23320068, 2013).
rheumatoid arthritis (3 papers, 2009 to 2025). A chronic, systemic autoimmune disorder characterized by inflammation in the synovial membranes and articular surfaces. "Schematic mechanism of inhibitor of differentiation 2 (Id2)‐mediated interferon‐γ (IFN‐γ) expression upregulation in the pathogenesis of rheumatoid arthritis (RA)." (PMID 40051059, 2025). "This research investigates the role of inhibitor of differentiation 2 (Id2) in the synthesis of pro‐inflammatory cytokines, specifically interferon‐γ (IFN‐γ) and interleukin‐17 (IL‐17), by various subsets of T cells, and its pathogenic role in rheumatoid arthritis (RA)." (PMID 40051059, 2025).
T-cell lymphomas (3 papers, 2008 to 2016). "Taken together, these data point to a regulatory circuitry that maintains thymocyte quiescence and provide a mechanism involving c-myc and p19Arf that underpins the development of T-cell lymphoma in Id2- and Id3-deficient T cells." (PMID 25691468, 2015). "Similarly to cHL, in T cell lymphomas, ID proteins including ID2, block lymphocyte differentiation and promote T-cell lymphomagenesis by antagonizing TCF3." (PMID 27166193, 2016). "Likewise, we found that Id2- and Id3-depleted murine T-cell lymphomas expressed relatively high levels of c-Myc expression." (PMID 25691468, 2015). "Eight of ten B-cell lymphomas and three of eight T-cell lymphomas were stained positively for ID2." (PMID 19099554, 2008). "Finally, mice depleted for Id2 and Id3 in T cells developed colitis as well as T-cell lymphoma." (PMID 25691468, 2015).
acute leukemia (2 papers, 2017 to 2022). A clonal (malignant) hematopoietic disorder with an acute onset, affecting the bone marrow and the peripheral blood. "Id2 and Id3 show different expression patterns and subcellular localization in acute leukemia subtypes: for example, AML is characterized by higher Id2 and Id3 expression than acute lymphoblastic leukemia (ALL)." (PMID 28122577, 2017).
acute promyelocytic leukemia (2 papers, 2017 to 2022). An aggressive form of acute myeloid leukemia (AML), characterized by arrest of leukocyte differentiation at the promyelocyte stage, due to a specific chromosomal translocation t(15;17) in myeloid cells. "Studies have shown that RARα antagonizes E protein activity by inducing transcription of ID1 and ID2 in human acute promyelocytic leukemia cells treated with all-trans-retinoic acid and ID1 and ID3 gene expression in normal human keratinocytes." (PMID 35503250, 2022). "In myeloid malignancies, ID1 and ID2 were lowly expressed in acute promyelocytic leukemia (APL) cells (NB4) and were rapidly induced upon all-trans retinoic acid (ATRA) treatment." (PMID 29190891, 2017).
anemia (2 papers, 2022). A reduction in the number of red blood cells, the amount of hemoglobin, and/or the volume of packed red blood cells. "Finally, Id2Δ/Δ chimeric mice had reduced survival due to anemia, leukocytosis, and BM failure compared with Id2+/+ chimeric mice (60% survival)." (PMID 35775482, 2022). "Furthermore, Id2-/- chimeric mice showed reduced overall survival due to anemia and BM failure compared to Id2+/+ chimeric mice indicating that ID2 is intrinsically required for HSC maintenance." (PMID 35990659, 2022).
Arthritis (2 papers, 2022 to 2025). Inflammation of a joint. "These mice and their littermates were used to establish a collagen‐induced arthritis (CIA) model to observe the effect of Id2 deletion in T cells on the incidence and severity of arthritis." (PMID 40051059, 2025). "This is in agreement with a previous rodent collagen-induced arthritis study by our group, where increased Id2 was indeed observed." (PMID 35693848, 2022). "In our study, deleting Id2 resulted in a limited incidence and disease score of arthritis but did not completely eliminate the induction of CIA in Id2fl/fl Cd4‐Cre+ mice." (PMID 40051059, 2025).
bone marrow failure (2 papers, 2020 to 2022). "ID2 monoubiquitination is critical to prevention of bone marrow failure in FA, but it is currently unknown how ID2-ub differs in its function to ID2." (PMID 32167469, 2020). "We report here that genetic ablation of Id2 in adult hematopoietic stem cells (HSCs) promotes increased HSC activation and differentiation, which results in HSC exhaustion and bone marrow failure over time." (PMID 35775482, 2022).
chronic lymphocytic leukemia (2 papers, 2015 to 2017). "Our study provides evidence for a pro-survival function of the ID2/ID3 proteins in chronic lymphocytic leukemia cells and also highlights these proteins as potential determinants of the pathobiology of this disorder." (PMID 25644253, 2015).
colitis (2 papers, 2015 to 2021). Inflammation of the colon. "Firstly, we confirmed that the expression of ID2 was reduced in the colon tissues of DSS-induced colitis mice and patients with ulcerative colitis (UC)." (PMID 34804049, 2021). "To investigate the function of the ID2 protein in the development of colitis, we generated the recombinant ID2 protein." (PMID 34804049, 2021). "In our study, ID2 was decreased in mice with DSS-induced colitis and UC patients; therefore, the decrease in ID2 expression might increase neutrophil and macrophage infiltration into colon tissue." (PMID 34804049, 2021). "The loss of inhibitor of differentiation-2 (ID2) could lead to the development of colitis in mice, supplementation with exogenous ID2 protein might be a potential strategy to ameliorate colitis." (PMID 34804049, 2021). "As the amino acid similarity between the human ID2 protein and mouse ID2 protein was approximately 99%, the anti-colitis effect of hID2 on mice considered to be effective in humans; thus, hID2 could be a promising agent for the treatment of UC." (PMID 34804049, 2021). "In addition, ID2 is essential for the intestinal mucosal barrier, and mice with Id2 and Id3 depletion develop colitis." (PMID 34804049, 2021). "In this study, we showed that exogenous supplementation with ID2 protein could efficiently protect mice against DSS-induced colitis by inhibiting NF-κB activation in neutrophils." (PMID 34804049, 2021). "We found that mice depleted for Id2 and Id3 expression developed colitis and αβ T-cell lymphomas." (PMID 25691468, 2015). "Numbers of granulocyte/macrophage progenitors and matured neutrophils in the peripheral organs and bone marrow were higher in Id2-deficient mice, and mice lacking Id2 and Id3 could develop colitis." (PMID 34804049, 2021). "In our study, we found that the expression of ID2 was decreased in the inflamed colon in UC patients and mice with DSS-induced colitis." (PMID 34804049, 2021). "We found that ID2 was mainly expressed in the mucosal epithelium in healthy colon tissue and was decreased in the inflammatory site of the colon in UC patients or mice with DSS-induced colitis." (PMID 34804049, 2021). "It was reported that mice lacking Id2 and Id3 could develop colitis." (PMID 34804049, 2021). "Therefore, it seems that ID2 expression is highly correlated with the prognosis of colitis, the role of exogenous ID2 protein supplementation in the treatment of UC has not been investigated, and whether this protein affects the function of neutrophils and macrophages is still unknown." (PMID 34804049, 2021).
cyst (2 papers, 2012 to 2015). A sac-like closed membranous structure that may be empty or contain fluid or amorphous material. "In this study, we present for the first time that TNFα regulates the expression and nuclear translocation of Id2 in renal epithelial cells, suggesting that cyst fluid TNFα may contribute to the upregulation and increased nuclear ld2 in ADPKD kidneys and Pkd1 mutant mouse kidneys." (PMID 26110849, 2015). "As RANKL belongs to the TNF family and TNFα has been found to exist in cyst fluid of ADPKD mice and patients, we have proposed that TNFα and RANKL regulate Id2 nuclear translocation in renal epithelial cells." (PMID 26110849, 2015).
esophageal squamous cell carcinoma (2 papers, 2021 to 2024). Esophageal squamous cell carcinoma (ESCC) is a type of esophageal carcinoma (EC) that can affect any part of the esophagus, but is usually located in the upper or middle third. "It has been reported that ID2 is highly expressed in esophageal squamous cell carcinoma (ESCC), serving as a marker for ESCC metastasis and prognosis." (PMID 38195969, 2024).
Hodgkins lymphoma (2 papers, 2008 to 2022). A heterogeneous group of malignant lymphoid neoplasms of B-cell origin characterized histologically by the presence of Hodgkin and Reed-Sternberg (HRS) cells in the vast majority of cases. "ID2 protein was expressed in 83.3% of this group of classical Hodgkin lymphoma, staining strongly in both cytoplasm and nucleus of the Hodgkin and Reed-Sternberg (HRS) cells." (PMID 19099554, 2008). "ID2 protein was expressed positively in 83.3% (50 out of 60) of the classical Hodgkin lymphomas." (PMID 19099554, 2008). "In our study, ID2 expression was expressed in the vast majority of classical Hodgkin lymphoma (83.3%) so it may be a potentially useful marker for identifying the HRS cell in classical Hodgkin lymphoma, independent of EBV status." (PMID 19099554, 2008). "Therefore, additional studies are needed to identify whether ID2, EBV-LMP1 and P16(INK4A) have similar diagnostic value and to explore the possible relationship between them in classical Hodgkin lymphoma." (PMID 19099554, 2008). "Taken together, ID2, EBV-LMP1 and P16(INK4A) were highly expressed in HRS cells of classical Hodgkin lymphoma, distinguishing the HRS cells from the background lymphocytes." (PMID 19099554, 2008). "We used the ID2, EBV-LMP1 and P16(INK4A) antibodies to investigate the possible role of the expression of the three proteins in 60 cases of Chinese classical Hodgkin lymphoma." (PMID 19099554, 2008). "Previous research also suggested that EBV-LMP1 and P16(INK4A) had a role in the carcinogenesis of classical Hodgkin lymphoma, but there was no corresponding investigation of associations between ID2, EBV-LMP1 and p16(INK4A), which might provide further understanding of the mechanism." (PMID 19099554, 2008). "The relationships between the expression of ID2, EBV-LMP1 and P16(INK4A) in Chinese classical Hodgkin lymphoma are unknown and need exploring." (PMID 19099554, 2008). "We show here that ID2 is not detectable in normal B cells but is strongly expressed in HRS cells of 83.3% of Chinese classical Hodgkin lymphoma (50/60)." (PMID 19099554, 2008). "It is suggested that ID2, EBV-LMP1 and P16(INK4A) could play an important role in the evolution of classical Hodgkin lymphoma, and be considered as potential adjunct markers to identify HRS cells in diagnosis." (PMID 19099554, 2008). "However, ID2 was not correlated with P16(INK4A) in this group of Hodgkin lymphomas (4.400 ± 2.980 vs 3.567 ± 2.557, Rho = -0.120, P = 0.191)." (PMID 19099554, 2008). "However, there is to date no study on the relationship between ID2 and EBV-LMP1 in Hodgkin lymphoma." (PMID 19099554, 2008).
inflammatory bowel disease (2 papers, 2015 to 2025). A spectrum of small and large bowel inflammatory diseases of unknown etiology.
intestinal tumor (2 papers, 2015 to 2018). "Given that the frequency of tumor development was age independent and Id2 expression was barely detectable in intestinal epithelial cells after birth, intestinal tumors in Id2−/− mice appeared to be derived from ectopic gastric cells formed in the small intestine during development." (PMID 29463648, 2018).
Listeria infection (2 papers, 2018 to 2024). "A previous study reported that Id2 was prominently upregulated in late CD8+ effector T cells and that its expression was maintained in memory cells in a murine model of Listeria infection." (PMID 38287103, 2024). "During Listeria monocytogenes infection, Id2 regulates gene expression by CD8+ T cells and determines the magnitude of effector responses, suggesting a mechanism involving Id2 governed and E protein-mediated survival and differentiation of mature T cells." (PMID 30687302, 2018).
liver fibrosis (2 papers, 2019 to 2023). "Id2 is a downstream target of BMP7 which antagonizes the TGF-β1-dependent fibro-genic activity in liver fibrosis and pulmonary myofibroblastic cells." (PMID 31803053, 2019). "Id2 inhibits HLH transcriptional factors such as MyoD in liver fibrosis, thereby reducing differentiation of hepatic stellate cells and promoting cell proliferation." (PMID 31803053, 2019). "Id2 also stimulates the production of MMPs in many cancers and liver fibrosis." (PMID 31803053, 2019).
multiple sclerosis (2 papers, 2020 to 2023). A progressive autoimmune disorder affecting the central nervous system resulting in demyelination. "Fibrinogen and Id2, the Id3-related protein, are upregulated in demyelinated multiple sclerosis lesions." (PMID 32005867, 2020).
neural tumors (2 papers, 2009 to 2012). "The transcription factor ID2 is an important repressor of neural differentiation strongly implicated in nervous system cancers." (PMID 22848373, 2012). "Given the established role of ID2 as a neural differentiation inhibitor, an enhanced expression of miR-9 and miR-103 may contribute to promote differentiation of cells from several neural tumours by hindering ID2 production." (PMID 22848373, 2012).
preeclampsia (2 papers, 2017 to 2023). Preeclampsia is a hypertensive disorder of pregnancy that is characterized by new-onset hypertension with proteinuria presenting after 20 weeks of gestation, and depending on mild or severe forms may initially present with severe headache, visual disturbances, and hyperreflexia. "Regardless, variants of ASB4 as well as those in other protein degradation mechanisms that control ID2 levels during trophoblast differentiation require further attention as risk factors for preeclampsia." (PMID 36768469, 2023). "A previous study showed that a subset of trophoblasts remains undifferentiated with sustained high ID2 expression in the placenta of Asb4−/− dams and that this plays a role in preeclampsia." (PMID 36768469, 2023). "Our data indicate that hyperinsulinemia perturbs the timely removal of ID2 and interferes with proper trophoblast differentiation, contributing to enhanced preeclampsia." (PMID 36768469, 2023). "Id-2 was downregulated at the mRNA and protein levels as the cytotrophoblast differentiated, but was maintained in placentas from women with preeclampsia, or in cells grown under hypoxic conditions in culture." (PMID 29348884, 2017). "Our demonstration that the placentas from HFD-Asb4−/− dams had a further increase in the expression of ID2 being sustained to further late stages suggests that the adverse effects of maternal obesity on preeclampsia begin at the trophoblast differentiation stage." (PMID 36768469, 2023). "While ASB4 is unlikely to be the sole molecule involved in the ID2 degradation process, its complete absence delays and impairs the placental differentiation process, leading to preeclampsia." (PMID 36768469, 2023). "Although this treatment regimen does not affect pregnancy in WT mice, pregnant mice lacking ASB4 with hyperinsulinemia show increased placental ID2 and decreased plasma VEGF and develop more severe preeclampsia-like phenotypes." (PMID 36768469, 2023).
prostate adenocarcinoma (2 papers, 2020 to 2024). "Given that JAK-STAT activation confers stemness to prostate adenocarcinoma, we performed GSEA on our data using the associated gene set and found it was activated after ID2 overexpression." (PMID 38254880, 2024). "Given the comprehension of the molecular mechanisms involved in NETD and the significance of ID2 in various cellular biological processes, we carried out a study to examine the function of ID2 in the process of the lineage transition of prostate adenocarcinoma." (PMID 38254880, 2024).
retinoblastoma (2 papers, 2015 to 2019). A malignant tumor that originates in the nuclear layer of the retina. "ID proteins are negative regulators of basic HLH (bHLH) transcription factors and, additionally, ID2 can bind and over-ride the tumour suppressor function of retinoblastoma (RB) tumour suppressor." (PMID 30642388, 2019).
small cell lung carcinoma (2 papers, 2009 to 2022). Small cell lung cancer (SCLC) is a highly aggressive malignant neoplasm, accounting for 10-15% of lung cancer cases, characterized byrapid growth, and early metastasis. "However, the increased expression of cytoplasmic ID2 was associated with better prognosis in small cell lung cancer patients." (PMID 35982951, 2022). "Research executed recently has demonstrated that Id2 might serve as a prognostic marker for patients diagnosed as having small-cell lung cancer or having poorly differentiated tumors in NSCLC." (PMID 35982951, 2022).
squamous cell carcinoma (2 papers, 2013 to 2019). A carcinoma arising from squamous epithelial cells. "Wang and colleagues demonstrated Id2 regulation on the proliferation of squamous cell carcinoma, in-vitro, via the NF-κB/CyclinD1 pathway." (PMID 31040905, 2019).
ventricular septal defect (2 papers, 2019). The presence of a defect (opening) in the septum that separates the two ventricles of the heart. "Id2 knock-out during embryonic E9.5-E14.5 leads to fatal defects in cardiac development, such as systemic and pulmonary circulation abnormalities, ventricular septal defect as well as myocardial hypoplasia." (PMID 31803053, 2019).
abdominal aortic aneurysm (1 paper, 2023). Enlargement and ballooning of the vessel that supplies arterial blood to the abdomen, pelvis and legs. "In the other study, inhibition of the noncanonical, TGF-beta 1-mediated PI3K/AKT/ID2 signaling pathway ameliorates abdominal aortic aneurysm." (PMID 37569462, 2023).
acute monocytic leukemia (1 paper, 2017). Acute monoblastic leukemia (AML-M5), is one of the most common subtypes of acute myeloid leukemia (AML) that is either comprised of more than 80% of monoblasts (AML-M5a) or 30-80% monoblasts with (pro)monocytic differentiation (AML-M5b). "However, ID2 was highly expressed in acute monocytic leukemia cells (THP-1) and was reduced by ATRA treatment." (PMID 29190891, 2017).
adenoid cystic carcinoma (1 paper, 2013). A malignant tumor arising from the epithelial cells. "We first determined the expression levels of Id1 and Id2 in four SGC cell lines: two adenocarcinoma of the salivary gland (HSG and HSY) and two adenoid cystic carcinoma (ACC2 and ACCM) cell lines." (PMID 23517130, 2013).